HGF (hepatocyte growth factor)
Diseases named in the same sentence as HGF in open-access papers (continued):
Sharing a sentence is not in itself a finding about the gene and the disease.
cancer (continued). "Biweekly intratumoral injection with HGF at a dosage of 30 μg/kg for 4 consecutive weeks enhanced the penetration of MDA-MB-436 cancer cells into the adjacent normal tissues, which was not seen with PBS injection." (PMID 22242160, 2012). "In addition, HGF/c-Met signaling induces epithelial-mesenchymal-transition (EMT), a pivotal event in the development of invasive and metastatic cancer progression in HCC cells." (PMID 22912725, 2012). "Both HGF and HGFR have been have been proposed as targets for cancer therapy." (PMID 23226201, 2012). "We also demonstrated that the HGF secretion, once established, can be maintained in NAFs without the continued co-culture with cancer cells." (PMID 22514714, 2012). "Amplification or over-expression of c-MET (the receptor for HGF) is a known genetic aberration and therapeutic target in squamous NSCLC and PAK1 may be a key effector for HGF/c-MET signaling in cancer." (PMID 21653999, 2011). "In addition, hepatocyte growth factor (HGF) is an important fibroblast-secreted protein that mediates development and progression of cancers." (PMID 21249190, 2011). "Therefore, overexpression of HAI-1 might play an important role in the inhibition of pro-HGF-activating proteases and KLK5, which induced inhibition of cancer cell growth." (PMID 40299447, 2025). "However, dysregulated activation of HGF/c-MET axis contributes to the development and progression of numerous human cancers, such as gastroesophageal adenocarcinoma, cholangiocarcinoma, colon cancer, renal cell carcinoma, glioblastomas, and lung cancer, among others." (PMID 40520181, 2025). "Notably, the cytotoxic effects of both extracts were more pronounced in cancer cells than in non-cancerous hGF cells, suggesting a level of selectivity." (PMID 40005959, 2025). "Moreover, we confirmed that the DU-145 cells themselves do not express HGF, using the Cancer Cell Line Encylopedia transcriptomic dataset." (PMID 40723207, 2025). "These insights required the generation of high-quality quantitative data on the dynamics of HGF signal transduction and thus shed new light on the complex regulation of MET in MASLD, while MET was so far primarily studied in the context of liver regeneration or cancer." (PMID 38216754, 2024). "Therefore, an in-depth study of HGF/c-MET mechanisms in the TME will enhance our biological perspective on tumors and provide a critical theoretical basis and potential targets for developing novel anti-cancer therapies." (PMID 39201787, 2024). "MDSC can also encourage the spreading of cancer cells through angiogenesis promotion, epithelial–mesenchymal transition (EMT) and mesenchymal–epithelial transition (MET) transition or secretion of tumorigenic factors such as TGFβ, hepatocyte growth factor (HGF) and IL-6." (PMID 36899926, 2023). "In CAF, lactate enhances NF-κB which acts on DNA, upregulates the synthesis and secretion of HGF cytokine which acts on the MET receptor and makes the tyrosine kinase receptor insensitive to tyrosine kinase inhibitors such as sunitinib and makes the cancer cells resistant to TKIs." (PMID 36761981, 2023). "The activation of the HGF/c-MET axis has been reported in various malignant tumors, regardless of whether there is a change in the MET genome." (PMID 37919751, 2023). "Although epithelial cells do not typically express HGF, one explanation for this finding could be that HGF transcription is switched on in cancer cells, triggering autocrine MET activation." (PMID 36799689, 2023). "To investigate whether EpCAM and HGFR activation cooperatively regulates cancer cell invasion, we examined EpCAM knockout cells with or without HGF treatment." (PMID 37543570, 2023). "MET amplification and overexpression correlate with constitutive activation of the Met RTK and downstream signaling pathways in the absence of the Met ligand, HGF, in cancer-derived cell lines, indicating that the induction of constitutive Met signaling underlies this clinical observation." (PMID 35249128, 2022).
cancer (continued). "Targeting the PAN domain in HGF could act as a multi-pathway target as it entirely shuts down the c-MET signaling cascade and downstream expression of relevant proteins known for their role in cancer prognosis and other diseases." (PMID 35778602, 2022). "Hepatocyte growth factor (HGF) is mainly secreted by CAFs and binds to the receptor, MET, on cancer cells, which activates the downstream signaling involving AKT, ERK/MAPK, and STAT3, and then enhances cancer cell survival, EMT, migration, invasion, proliferation, and chemotherapy resistance." (PMID 35327514, 2022). "However, according to our data, it is likely that TGFβ1 targeting will not be sufficient to abolish HGF production that, as already mentioned, is essential to drive cancer cell invasion." (PMID 36010567, 2022). "In addition, EVs containing secretory epidermal growth factor receptor (EGFR) derived from GC cells effectively activate hepatocyte growth factor, which in turn binds to c-MET receptors on migrating cancer cells to promote the homing of metastatic cancer cells." (PMID 35886934, 2022). "MAP4K4 implication in HGF-induced internalization of membrane transport proteins and drug transporters indicated a potential therapeutic benefit of targeting this function of MAP4K4 during chemotherapy, which remains one of the first-line treatments for cancer patients." (PMID 35296518, 2022). "Various monoclonal antibodies (mAbs) and anticalines targeting c‐Met or its ligand (HGF), for example, DN30, rilotumumab, onartuzumab, and PRS‐100, have been recently tested in both preclinical and clinical trials, with encouraging results for the management of cancer." (PMID 35292998, 2022). "Paracrine production of growth factors and cytokines, including hepatocyte growth factor (HGF), insulin‐like growth factor (IGF), and stromal‐derived factor (SDF‐1/CXCL12) support a protumourigenic, chemotherapy‐resistant and immune‐suppressive environment in a variety of cancers." (PMID 35533046, 2022). "While it can be difficult to identify the causative gene in a copy number amplification in cancer, we show that high telomeric content is associated with RAD21 and HGF but not nearby oncogenes, and furthermore, we identify a minimal amplified interval around RAD21 consisting of 8q23.1–q24.12." (PMID 35227290, 2022). "For example, genes that encode DRs such as DCC, neogenin, UNC5B, UNC5C, or TrkC are repressed in multiple cancer types, while cancer cells can also escape DR‐mediated apoptosis through autocrine overexpression of ligands including DKK1, Netrin‐1, NT‐3, Sema3E, or HGF." (PMID 34542930, 2021). "Several signaling pathways, including hepatocyte growth factor (HGF), epidermal growth factor (EGF), transforming growth factor beta (TGF-β), Notch, and Wnt/β-catenin, regulate EMT, and the activation of Wnt/β-catenin pathway is commonly seen in many malignant tumors." (PMID 34337054, 2021). "Therefore, specific binding of rilotumumab to HGF neutralizes the interaction between HGF and c-MET and inhibits c-MET phosphorylation and downstream signaling, resulting in inhibition of cancer cell proliferation, survival, and invasion through partial antagonism of c-MET phosphorylation." (PMID 33466394, 2021). "The HGF/MET axis, along with interaction with other tyrosine kinases, can activate multiple signaling cascades in the cells, including Wnt/ß-catenin, Janus kinase/STAT, RAS/MAPK, PI3K/AKT, and Src, which among others can take a highly important role in cancer development." (PMID 34217156, 2021). "Both HGF and IGF1 activated signaling pathways lead to BC cell proliferation, migration and invasion, and are critically involved in the induction/maintenance of EMT and cell stemness, which are fundamental in metastatic spread and resistance to anti-cancer treatments." (PMID 34195201, 2021).
cancer (continued). "Therefore, although the HGF/c-MET pathway, immune cell infiltration and immune pathway scores integrated in this study can satisfy the prediction of 11 cancers, it is difficult to find a feature that could be widely used in all cancers." (PMID 34261467, 2021). "Our data indicate that the GAS6-AXL and HGF-MET signal pathways markedly contribute to cancer cell migration and invasion in an independent manner, suggesting that simultaneous inhibition of these two pathways contributes to the anti-cancer effects of cabozantinib." (PMID 32055714, 2020). "Thus, the observed absence of metastasis in the triple therapy group may also reflect the important contribution of the HGF/c-MET inhibition component of the triple therapy, which significantly downregulates EMT of cancer cells." (PMID 32203220, 2020). "In patients with intracranial tumors in the perioperative period there are increased plasma levels of the proangiogenic factor, i.e. HGF, compared to people with no cancer diagnosis, as evidenced by increased angiogenic and mitogenic activity in these patients." (PMID 32607415, 2020). "Furthermore, HGF promotes the up-regulation of glucose intake in cancer cells, inducing the expression of the membrane glucose transporter GLUT-1; the enhanced intake of glucose allows cancer cells to quicken their metabolism and their replication rate." (PMID 33143050, 2020). "Additionally, this HGF-induced FAK activation also upregulates MMP-1, MMP-9, MMP-14 (all of these MMPs play an important role in cell invasion, thus increasing invasiveness of cancer) in gallbladder, prostate, and liver cancers." (PMID 33271944, 2020). "Interestingly, when HGF inhibition was combined with c-MET inhibition and chemotherapy (triple therapy) in mouse models of early and advanced PC, a significant inhibitory effect was observed on cancer metastasis." (PMID 33271944, 2020). "Additionally, TNF-α, although not alone, was capable of upregulating MET (receptor for HGF) expression and promoting the antitumor activity of neutrophils in a variety of cancer types." (PMID 32117288, 2020). "It has also been shown that HGF activates the phosphatidylinositol-3-kinase/protein kinase-B (PI3K/Akt) and nuclear factor kappa-light-chain-enhancer of activated B cells (NF-κB) signalling to promote HPSE in cancer cells, resulting in a poor clinical prognosis in gastric tumours." (PMID 33256730, 2020). "Through activating canonical or non-canonical signaling pathways, the HGF/c-Met axis mediates a range of oncogenic processes such as cell proliferation, invasion, apoptosis, and angiogenesis and is increasingly becoming a promising target for cancer therapy." (PMID 32083078, 2020). "Although to our knowledge c-MET expressing lymphocytes have not be found in human NSCLC cancer there is evidence that subsets of lymphocytes may response to HGF in other types of human cancer." (PMID 32117721, 2020). "It is well known that HGF/c-MET signaling activates MAPK cascades enhancing cancer cell proliferation and Akt cascades increasing the anti-apoptotic effects, which could eventually increase the drug tolerance capacity in various cancers." (PMID 30680600, 2019). "As a result, differentiated CAFs induce motility and migration in cancer cells via induction of EMT through secretion of a number of soluble factors which include TGF-β1, IL-6, and hepatocyte growth factor (HGF), and/or by direct chemokine attraction through CXCL1 and CCL1." (PMID 31850055, 2019). "A more recent study has shown, by in vitro and in vivo experiments, that HSC-secreted HGF might reduce HCC sensitization to chemotherapeutic agents by promoting epithelial-mesenchymal transition (EMT) and cancer stem cell (CSC)-like properties through the HGF/c-Met pathway." (PMID 30959975, 2019).
cancer (continued). "This is the first study to assess the potential of BFE in cancer and we examined the effects of BFE on TNBC cell proliferation, migration, matrix-adhesion, invasion, angiogenesis and the activation/phosphorylation of the c-Met receptor under the influence of HGF." (PMID 30314527, 2018). "However, we found that murine HGF is not completely inactive on human airway epithelial cells or cancer cell lines but stimulates the phosphorylation of GRB2-associated-binding protein 2 (GAB2) and signal transducer and activator of transcription 6 (STAT6)." (PMID 29771943, 2018). "Moreover, mounting experimental and clinical evidence have also suggested a central role for the signaling networks operating to promote a metastatic and/or therapeutic resistance cascade in cancer development that involves interactions of AR, TMPRSS2, HGF and c-MET with critical components of TMEs." (PMID 29587825, 2018). "Moreover, the upregulated paracrine HGF, which binds the c-MET receptor on the migrated cancer cells, provides fertile ‘soil' for the ‘seed', facilitating the landing and proliferation of metastatic cancer cells." (PMID 28393839, 2017). "We observed that both HGF- and CsA-induced signals increased the number of migrated cells that filled the wound area compared with control cells; whereas HNK significantly inhibited the increased migration of cancer cells following treatment with both HGF and CsA." (PMID 28724911, 2017). "Thus, HGF/MET-driven aberrant morphogenesis plays a crucial role not only in cancer but in IPF, as well." (PMID 27590450, 2016). "Among them, HGF (also known as scattering factor) activates the c-Met signaling pathway, thereby, increasing the invasive and metastatic potentials of the cells and allowing the survival of cancer cells in the bloodstream in the absence of anchorage." (PMID 26919096, 2016). "hepatocyte growth factor (HGF), interleukin-6 (IL-6) and other cytokines/chemokines derived from mesenchymal cells may promote de-differentiation, although their roles in triggering cancer cell EMT are not fully understood yet." (PMID 26985909, 2016). "It is expected that ddPCR may have good application prospects in molecular cancer diagnosis, for example in the study of phosphoinositide-3-kinase, catalytic subunit α (PIK3CA), MET proto-oncogene (MET; hepatocyte growth factor) and Kirsten rat sarcoma viral oncogene homolog (K-RAS)." (PMID 25780439, 2015). "HGF-dependent activation of Met leads to receptor dimerization, tyrosine autophosphorylation, and initiation of down-stream signaling, including activation of MAPK, PI3K/Akt, and STAT pathways, all of which play an important role in cancer cell proliferation and survival." (PMID 26932375, 2014). "Because of the widespread expression of MET and HGF in cancer, their expression has been analyzed for cancer severity, and the degrees of expression of MET and HGF are believed to indicate the progression of disease as well as serve as prognostic markers for some forms of cancer." (PMID 28548073, 2014). "Thus, the dual effects of NK4 (i.e., HGF-antagonist and angiogenesis-inhibitor) could provide a new concept whereby NK4 may prove therapeutic for malignant tumors." (PMID 23296269, 2013). "However, in our study, only the systemic HGF levels were correlating with absolute numbers of circulating MSCs (r = 0.72, P < 0.03), but not with VSELs (r = 0.21, P = 0.28) in patients with malignancy." (PMID 23672538, 2013). "Additionally, hepatocyte growth factor (HGF)-MET receptor signaling provides important signals for cell survival and migration in cancer cells; thus, these molecules have also emerged as promising molecular targets for cancer therapy." (PMID 23426935, 2013). "Temsirolimus suppressed VEGF production in these cancer cells in the presence or absence of HGF." (PMID 23690929, 2013). "Therefore, MMP-2 may be the HGF-responsive mediator, and its degradation of ECM may lead to subsequent cancer migration and metastasis." (PMID 23320110, 2013).
cancer (continued). "Hence, HGF increased levels in all patient groups except in CHC confirm and suggest that this protein can be used as index for predicting, in patients with T2D, the progression of chronic inflammation to cancer." (PMID 22745767, 2012). "The results showed that HGF did not influence cancer cell viability and proliferation." (PMID 22242160, 2012). "Moreover, cancer-associated fibrosis is marked by chronic inflammation within cyto/chemokines (i.e., IL-6, IL-8, IL-17A, and IL-1α), and growth factors (i.e., SDF-1, HGF, PDGF, and TGF-β) are released by both malignant and non-cancer cells, contributing to tumor cell proliferation and invasion." (PMID 40649899, 2025). "There is a strong interaction between fibroblasts and epithelial cells which may be involved in carcinoma initiation and promotion, including secretion of the fibroblast growth factor (FGF) family, the IGF family, the EGF family, hepatocyte growth factor (HGF), and the TGF-β family." (PMID 34359821, 2021). "Moreover, it has been shown that cancer exosomes could trigger MSC differentiation into pro-angiogenic and pro-invasive myofibroblasts, secreting high levels of matrix-regulating factors (MMP-1, -3, and -13), VEGF-A, and HGF." (PMID 32260433, 2020). "Although MACC1 and S100A4 are involved in different biological pathways, that is, MACC1 as a key regulator of HGF‐MET signaling and S100A4 as a transcriptional target of β‐catenin/T‐cell factor signaling, our data suggest that MACC1 and S100A4 might be co‐regulated in cancer." (PMID 30927479, 2019). "Notably, these cancer biomarkers functionally comprised of several cytokines (IL-6, MIF, TGF-α, TNFα), apoptosis-related proteins (sFas, sFasL, TRAIL), growth and angiogenic factors (FGF2, HGF, SCF, VEGF), hormones (leptin, prolactin) and other biomarkers (AFP, OPN), but not carcinoma antigens." (PMID 31089160, 2019). "In addition to pro-HGF/SF, matriptase has multiple other substrates, such as protease activated receptor 2, pro-prostasin and pro-MSP, which may be involved in cellular context- and environment-dependent effects of matriptase on cancer progression." (PMID 25268161, 2014). "Moreover, in this model, hepatocyte growth factor (HGF) was up-regulated and complementary activation of the HGF receptor MET was detected in tissues where TβRII had been ablated, which implicates this paracrine signaling network as a potential mechanism for regulation of carcinoma development." (PMID 22943793, 2012). "To define the role of the HGF/MET axis in this complex process, we genetically knocked out the MET gene in cancer cells that were not dependent on MET signaling for their growth." (PMID 37345079, 2023). "To disentangle the role of HGF (Hepatocyte Growth Factor) and MET ligand/receptor axis in this complex process, we genetically knocked out the MET gene in cancer cells in which MET is not the oncogenic driver." (PMID 37345079, 2023). "Mechanistically, they show that cancer cells treated with TKIs targeting MET and EGFR secrete higher levels of lactate, which then instructs CAFs to secrete HGF, resulting in the non-responsiveness of cancer cells to the treatment." (PMID 34298736, 2021). "Because the biochemical and cell biological features of TMPRSS13 are still relatively uncharacterized and have not been studied in the context of cancer, the only two candidate mammalian substrates for TMPRSS13 reported to date are pro-HGF and ENaC25,26." (PMID 32807808, 2020). "Studies with our 3D organotypic cultures (involving the seeding of cancer cells on top of PSC-containing collagen matrices) showed that inhibition of HGF and c-MET (either alone or in combination) did not alter cancer cell proliferation." (PMID 32203220, 2020).